CXCR2 (C-X-C motif chemokine receptor 2)
Diseases named in the same sentence as CXCR2 in open-access papers (continued):
Sharing a sentence is not in itself a finding about the gene and the disease.
tumor (continued). "CXCR2 selective inhibitors (e.g., SB225002) have shown promising efficacy in tumor therapy." (PMID 40979214, 2025). "Recent research indicates that the CXCL8/CXCR2 signaling pathway is crucial for the recruitment of myeloid-derived suppressor cells (MDSCs) into the tumor microenvironment (TME), with MDSC accumulation contributing to immune suppression and tumor progression." (PMID 40006729, 2025). "CXCR2 inhibitors, such as SX-682, impair PMN-MDSC trafficking, which subsequently enhances the efficacy of T cell- and NK cell-based immunotherapies by allowing better immune cell infiltration and activity within the tumor." (PMID 40109854, 2025). "Targeting CXCR2 with specific antagonists or antibodies could reduce the number of TANs in the TME and, consequently, diminish the pro-tumor effects of these cells." (PMID 40486614, 2025). "We next set out to engineer CXCR2-targeted biotherapeutic molecules that could modulate this pathway and disrupt myeloid cell trafficking to PDAC tumor sites." (PMID 40427538, 2025). "To determine whether PTEN restoration and CXCR2 depletion could reactivate antitumor immunity by remodulating the immune microenvironment of BmCRPCs, we analyzed MDSC (CD11b+Gr-1+) infiltration in tumor tissues after 2 weeks of treatment." (PMID 40860155, 2025). "Tumor‐derived oxysterols can bind to and activate the G protein‐coupled receptor C‐X‐C motif chemokine receptor 2 (CXCR2), rather than the LXR, to recruit neutrophils, promote angiogenesis, and induce immunosuppression, thereby facilitating tumor growth." (PMID 40145543, 2025). "Modulation of oral commensal bacteria and immune mediators such as IL-17–producing γδ T cells or CXCL2/CXCR2 could aid in monitoring OSCC progression and in developing adjunct therapies to mitigate tumor-promoting inflammation." (PMID 40924302, 2025). "Studies have demonstrated that CXCR2 inhibitors, including SB225002 and SX-682, and neutralizing antibodies can effectively block PMN-MDSCs infiltration, thereby slowing tumor progression and restoring responsiveness to immunotherapy in refractory cancer models." (PMID 40227814, 2025). "The dual role of neutrophils in cancer is recognized, with either anti-tumor effects, such as growth of tumor-associated microbiota limitations and metastasis suppression in experimental CRC, or tumor progression and metastasis support via the CXCL1/CXCR2 chemokine axis activation." (PMID 41283264, 2025). "Given the observed coexpression of CXCR2 and CD47, we propose that the IL-8/CXCR2 pathway may regulate CD47 expression, thereby impairing TAM recruitment and increasing tumour immune evasion." (PMID 41163221, 2025). "Together, these findings suggest that IL-8/CXCR2-induced metabolic reprogramming promotes CD47 expression by increasing AC-CoA levels, which increases p65 acetylation and subsequent NF-κB pathway activation, thereby supporting tumour immune evasion." (PMID 41163221, 2025). "To investigate whether CXCR2 mediates PI3K/AKT signaling during fibroblast activation and to explore tumor–stroma metabolic interactions, we isolated primary fibroblasts from resected human PDAC tissues and expanded in culture." (PMID 41444422, 2025). "In a study on CXCL1 promoting the mutual activation of cancer-associated fibroblasts and OSCC cells, the results showed that CXCL1 neutralizing antibody and CXCR2 antagonist SB225002 attenuated the invasion-promoting effect of CAF-CM, confirming the importance of CXCL1 in tumor invasion." (PMID 41445742, 2025). "The advent of targeted therapies, such as CXCR2 antagonists, TGF-β blockers, metabolic reprogramming agents, and engineered nanoparticles, has opened new clinical avenues for modulating neutrophil behavior to enhance anti-tumor immunity." (PMID 40486616, 2025).
tumor (continued). "Another study revealed that tumor-derived chemokines such as IL-8 and CXCL5 drive the recruitment of MDSCs into patients with Enz-treated CRPC by binding to CXCR2, highlighting the blockade of CXCR2 as a potential strategy to increase Enz sensitivity 21,22." (PMID 40860155, 2025). "Additionally, CXCR2 antagonists such as SB225002 and SCH-527123 have shown promising preclinical anticancer activity, inhibiting tumor cell proliferation, migration, and therapy resistance across multiple cancer types." (PMID 40490643, 2025). "The results revealed that in both models, regardless of cellular origin, the group treated with CXCR2 CAR-T demonstrated a statistically significant deceleration of tumor growth from day 28 compared to the CAR-T group." (PMID 38430267, 2024). "Among the ligands of CXCR2, CXCL1, 5, 7, and 8 are considered major angiogenic chemokines in NSCLC, with the overall level of angiogenic chemokines being the strongest predictor of tumor vessel density in NSCLC." (PMID 39114657, 2024). "Expression and localization of IL-8, CXCR1, and CXCR2 in normal tissues and HNSCC tumors were evaluated with a commercially available tissue array containing 70 tumor cases of unknown HPV status and 10 normal tissues." (PMID 39639338, 2024). "However, due to the higher expression of CXCR1 relative to CXCR2, CXCL8/IL-8 is more significant in this tumor’s development and function." (PMID 38673949, 2024). "For example, IL-8 produced by immunosuppressive cells like cancer cells, mast cells, macrophages, and neutrophils can promote TCSCs self-renewal, sphere formation, and tumor initiation capacity by attaching to TCSCs cell surface CXCR1 and CXCR2 via autocrine or paracrine pathways." (PMID 39776907, 2024). "The presented results indicate the significant correlation between the CXCL12, CXCR4, CXCL8/CXCR2, M-CSF, MMP-2, MMP-9 ADAM17, ADAMTS-6, and CLDN7 levels and tumor stage, as well as the clinicopathological parameters of OC, such as the presence of lymph node and/or distant metastases." (PMID 38673838, 2024). "However, the results herein demonstrated that, despite inhibiting tumor growth, CXCR1 was more effective in regulating EMT marker expression than CXCR2." (PMID 39766038, 2024). "The expression of miR-141 in tumour cells decreases and the production of CXCL1 increases during MPE development, and miR-141 recruits Tregs into MPE via CXCR2, resulting in an enhanced immunosuppressive effect of Tregs that promotes the immune escape of tumour cells and exacerbates MPE formation." (PMID 38475858, 2024). "Some studies have demonstrated that by inducing the Warburg effect in the tumor microenvironment (TME), activated C-X-C motif chemokine ligand 1/2 (CXCL1/2) binds to C-X-C motif chemokine receptor 2 (CXCR2), recruiting MDSCs and other cells, thereby fostering tumor growth and immune escape." (PMID 39192979, 2024). "Then, we measured the expression of various cytokines in tumor tissues by ELISA and found that there was a statistical difference in IL-8 along with a group-by-group decreasing trend in UTD group, CAR-T group, and CXCR2 CAR-T group." (PMID 38430267, 2024). "Pharmacological targeting of neutrophils and their chemokine receptor CXCR2, or genetic ablation of the neutrophil recruiting chemokine Cxcl1, results in extended survival of PDGFB-driven tumor-bearing qMCP-deficient mice but not WT tumor-bearing mice." (PMID 37012245, 2023). "Once infiltrated into the tumor tissues, however, neutrophils appear to lose the expression of both CXCR2 and CD44, an event that might help neutrophils to stay in tumor tissues." (PMID 36921037, 2023). "We hypothesize that DOX and anti-CXCR2 antibody can affect the enrichment of macrophages, especially M2-like macrophages, in the TME and can thus affect tumour progression." (PMID 37037815, 2023).
tumor (continued). "We screened top ten upregulated genes in chemokine signaling pathways and the top fifty up-regulated genes in all sequenced genes, and consistently found CXCL2 and its receptor CXCR2 were significantly upregulated in CCL20-modulated PMN-MDSCs and tumor cells, respectively." (PMID 36859354, 2023). "While CXCL8/CXCR1 mainly increases tumor cell proliferation, CXCL8/CXCR2 enhances angiogenesis." (PMID 36614308, 2023). "Thus, we constructed the orthotopic KPC model and administered the CXCR2 inhibitor (SB225002), AB680+anti‐PD‐1 therapy, or a combination of those drugs 3 days after tumor transplantation." (PMID 37867243, 2023). "On the one hand, myeloid-derived suppressor cells (MDSCs) can produce NETs under the stimulation of IL-8, and at the same time, in the tumor microenvironment, MDSCs can produce chemokines such as CXC chemokine receptor 1(CXCR1) and CXCR2 agonists to promote the production of NETs." (PMID 37373412, 2023). "If we could examine the downstream effect of CXCR1 compared to CXCR2 when bound to CXCL8 or CXCL6, we could evaluate which downstream pathways elicit pro-CSC-like characteristics in the tumor cells." (PMID 36831112, 2023). "In TNBC, tumor cell-derived conditioned medium induces a polarized morphology and activation of neutrophils, mediated by cytokines such as TGF-β and the ligands for the chemokine receptor CXCR2, i.e., CXCL1/2/3." (PMID 37496019, 2023). "Preclinically, blocking the CXCR2-axis showed less tumor outgrowth in mouse experiments, but no advantage was seen in clinical trials." (PMID 38069130, 2023). "MDSCs have several chemokine receptors, including CCR1, CCR2, CCR3, CCR5, CCR12, CXCR2, CXCR4, and C5aR1.25In the current study, MDSCs may express CCR1, the receptor of CCL9, which mediated the migration of MDSCs to tumor tissue." (PMID 38046278, 2023). "When CXCR2 is inhibited, native OBSC TME seems to mediate tumor-permissive effects, and even tumor-promoting effects are produced in combination with dexamethasone treatment—this phenomenon is contrary or missing when PLX5622-pretreatment of the OBSC was performed." (PMID 38069130, 2023). "Further potential avenues proposed to block protumor effects of TANs could be achieved by targeting the CXCL-8/CXCR-1/CXCR-2 axis, or targeting substances produced by TANS which promote tumor growth." (PMID 37143649, 2023). "Similarly, lymphatic endothelial cells (LECs) have shown to recruit MDSCs to the tumor microenvironment and increase tumor progression in TNBC cells via pro-angiogenic receptor CXCR2 on MDSCs." (PMID 37056346, 2023). "However, after tumor formation, the same assay indicated that ~ 30% of GFP-positive cells in Braf/Pten/Cxcr2−/− tumors expressed CXCR2." (PMID 37270599, 2023). "Moreover, some cytokines, such as CXCL1/CXCR2 axis, G-CSF, GM-CSF and VEGF-C, have been confirmed to be involved in the recruitment of MDSCs in tumor-bearing mice." (PMID 37268941, 2023). "In addition, the CXCR2 antagonist can reduce PMN-MDSC accumulation, increase CD8 T cell infiltration in the tumor, and further enhance the efficacy of anti-PD-1 in tumor-bearing mice." (PMID 38026944, 2023). "Then, we investigated whether the TC microenvironment could recruit mast cells to the tumor stroma by chemotaxis by screening the chemokine receptors involved in mast cell migration, including CCR2, CCR5, CXCR1, CXCR2, CXCR4, and CXCR7." (PMID 37042867, 2023). "Though the CXCR2 chemokine receptor is known to play a key role in cancer growth and response to therapy, a direct link between expression of CXCR2 in tumor progenitor cells during induction of tumorigenesis has not been established." (PMID 37270599, 2023). "Raychaudhuri and Vogelbaum discovered that in GBM, the tumor cells do not express CXCR2; they only express CXCR1 while also expressing CXCL8." (PMID 36831112, 2023).
tumor (continued). "Moreover, tumor‐derived CXCL1 and CXCL8 increased CXCR2, ERK and JNK pathways‐dependent production of VEGFA and MMP9 in neutrophils, which led to lymphangiogenesis." (PMID 36670069, 2023). "Despite the evident inhibitory effects on RT-induced neutrophil infiltration, CXCR2 blockade did not significantly affect other tumor-infiltrating myeloid cell populations." (PMID 38067390, 2023). "In addition to tumor cells, CXCR1 and CXCR2 are also important chemokine receptors of myeloid immune cells, such as neutrophils and monocytes." (PMID 37403022, 2023). "This is consistent with current scientific knowledge, as NK cells have low expression of CXCR1 and CXCR2 and are, therefore, not recruited to the tumor microenvironment by CXCR2 ligands." (PMID 37686093, 2023). "In contrast, M-MDSCs have much lower CXCR2 expression and are not recruited to the tumor microenvironment by CXCR2 ligands, but instead by CCL2." (PMID 37686093, 2023). "We further investigated the expression of CXCR2 and found that the absence of ARNT significantly promoted the expression of CXCR2 in neutrophils under tumor or physiological conditions." (PMID 36859266, 2023). "Furthermore, CXCR1 and CXCR2 antagonists inhibit CRC liver metastasis by decreasing angiogenesis and inducing tumor cell apoptosis in vivo." (PMID 35791509, 2022). "CXCR2 is not normally expressed on T cells but is specific for a variety of ligands overexpressed on a range of tumours, including CXCL1, CXCL2, CXCL5, and CXCL8." (PMID 35205725, 2022). "At 72 h, colon and tumour tissue were collected and examined for histopathological changes and RT-PCR for genes of interest; TLR4, MD-2, CD-14, MyD88, IL-6, IL-6R, CXCL2, CXCR1, and CXCR2." (PMID 35962138, 2022). "In addition, both preclinical and clinal trials indicated that targeting CXCR2 and CXCR4 increased the efficacy of immunotherapy by reducing tumor neutrophil infiltration and promoting adaptive immune responses." (PMID 35158948, 2022). "Tumor-derived EVs from a metastatic human melanoma cell line (MV3), for example, have been shown to induce neutrophil chemotaxis through the CXCR2/PI3K-Akt axis and to promote the formation of NETs, which play a crucial role in inducing cancer-associated thrombosis and tumor drug resistance." (PMID 36591453, 2022). "In models of NASH-HCC lacking response to ICI, the combination of a CXCR2 antagonist with anti-PD1 suppressed tumour burden and extended survival." (PMID 35477863, 2022). "Also, it will be important to determine precisely how and why combined CXCR2 antagonism and anti-PD1 treatment selectively induces proliferative immature neutrophils in the tumour." (PMID 35477863, 2022). "This could be at least partially reversed by combined targeting of CXCR2 and CCR2, demonstrating a critical role for collagen and CAFs in the orchestration of the tumour microenvironment (TME)." (PMID 35533046, 2022). "CXCR2-modified CAR-T cells could also accelerate trafficking in vivo and tumor-specific accumulation." (PMID 36168626, 2022). "Although blocking the interaction of interleukin 8 with CXCR1 and CXCR2 enhanced lapatinib-inhibited CSC activity and suppressed tumor growth in a xenograft mouse model, concern remains that targeting individual GPCRs may not be effective for eradicating CSCs." (PMID 35406489, 2022). "Similar to the mouse models, CXCR2 expression was limited to infiltrating immune cells and was absent on tumour epithelium within HCC in patients." (PMID 35477863, 2022). "In human colorectal cancer mouse models, IL-8 induces significant increases in CD31+ peritumoral vasculature, while CXCR2 knockout results in significantly reduced tumor growth, potentially due to lack of IL-8 signaling." (PMID 35565306, 2022). "Furthermore, BC-MSCs recruit CXCR2+ neutrophils into TME, inducing a significant increase in expression of metastasis-related genes (CXCR4, CXCR7, MMP12, MMP13, IL-6 and TGF-β) in tumor cells and consequent metastasis." (PMID 35842634, 2022).
tumor (continued). "As-T cells generated more IL-8 to promote tumor angiogenesis through its paracrine effect; and IL-8 receptors, C-X-C chemokine receptor type 1 (CXCR1), and CXCR2, are required for As-T cells to induce endothelial cell proliferation, migration, and tube formation, thus enhancing tumor angiogenesis." (PMID 35241635, 2022). "Moreover, the chemokine receptor CXCR2, which is important for NK cell recruitment, is downregulated in NK cells from PDAC patients, leading to impaired tumor infiltration." (PMID 35205732, 2022). "CXCL5, a member of the proangiogenic subgroup of the CXC family, has been found to play a key role in tumor development and metastasis by interacting with its GPCR, CXCR2, and activating both the traditional EGFR and RSK1/2/AKT/ERK pathways, leading to phosphorylation of HSP27 (Heat Shock Protein)." (PMID 36164329, 2022). "Ten chemokine receptors (CXCR1, CXCR2, CXCR4, CXCR6, CCR3, CCR6, ACKR4/CCRL1, CCLR2, CX3CR1, and ACKR1/DARC) were identified as differentially expressed from the DEG analysis between Black, White and Asian patient normal and tumor samples." (PMID 35754051, 2022). "Additionally, PAD4 promotes the metastasis of gastric tumors by regulating the expression of CXCR2, keratin K14 (KRT14) and TNFβ, which can accelerate angiogenesis, cell proliferation, migration and tumor immune microenvironment establishment." (PMID 35574410, 2022). "While initial correlative studies had shown a reduction in TAMs and influx of tumor-infiltrating lymphocytes, subsequent analyses demonstrated that CCR2 inhibition resulted in compensatory increases in CXCR2+ TANs, putting into question the rationale of targeting a single myeloid subset." (PMID 36077755, 2022). "Moreover, it has been demonstrated that primary tumor CAFs enhance invasion of tumor cells, via CAF chemokine (C-X-C motif) ligand 1 (CXCL1) secretion and interaction with C-X-C motif chemokine receptor 2 (CXCR2) in the tumor cells." (PMID 34201840, 2021). "A shorter survival may be due to a greater tumor and ascites burden in the HFD-fed CXCR2 WT and cKO, respectively." (PMID 34638514, 2021). "The closely related chemokine receptors, CXCR1 and CXCR2, expressed on neutrophils and MDSCs are responsive to several chemokines produced by tumor cells and other cell types and are now well recognized as viable targets in the adjunctive therapy of cancer." (PMID 34168563, 2021). "In healthy tumor-free mice, cell surface expression of CXCR4 was significantly higher in chronologically aged (BrdUneg) than in non-aged (BrdUpos) blood neutrophils, whereas cell surface expression of L-selectin/CD62L and CXCR2 was significantly decreased." (PMID 34876407, 2021). "In brief, especially CXCR2 and CXCR4 mediate tumor angiogenesis." (PMID 34203660, 2021). "Furthermore, the tumor-induced plasticity of NDN resulted in the formation of a new cell subset, specifically the LD-NDN, with the CXCL1/CXCR2 axis playing an important role in this formation." (PMID 34680231, 2021). "In further investigation, it was found that inhibition of CXCR2 can have other significant effects in PDAC, such as limiting tumor metastasis, creating a favorable T-cell balance within the TME, enhance response to chemotherapy, and to anti PD-1 therapy, and extending overall survival." (PMID 34771675, 2021). "However, that study have suggested that the regulation of IL-8 within the tumor and microenvironment play a critical role, but the impact of tissue microenvironment-derived CXCL8 and CXCR2 to date remains difficult to evaluate." (PMID 34025668, 2021). "We found that tumor purity was only negatively related to three immune genes, namely, CD8A (R = −0.18, p = 1.06 e-06), CXCR2 (R = −0.18, p = 2.90 e-07), and TNFRSF14 (R = −0.21, p = 2.58 e-09), but not to other immune-related genes, including the well-known PD1, PD-L1, and CTLA4." (PMID 34925437, 2021).